MIR4786 (microRNA 4786)
Synonyms: hsa-mir-4786; mir-4786
Gene: MicroRNA gene on chromosome 2 (239,943,015 to 239,943,094, reverse strand). Ensembl gene ENSG00000264279.
Homologues: Orthologues: chimpanzee MIR4786 (100% identical).